RHOA (ras homolog family member A)
Diseases named in the same sentence as RHOA in open-access papers (continued):
Sharing a sentence is not in itself a finding about the gene and the disease.
prostate carcinoma (66 papers, 2005 to 2025). A carcinoma that arises from epithelial cells of the prostate gland. "In another investigation the observed CB1 dependent inhibition of motility in prostate carcinoma cells was caused by an inhibition of the small GTPase RhoA, with an accompanying increase in Cdc42 and Rac1 activity." (PMID 30753211, 2019). "Through additional mechanistic studies, we recently discovered that both TPα and TPβ directly interact with and regulate signalling by protein kinase C-related kinase (PRK) 1, a RhoA effector widely implicated in prostate cancer." (PMID 26296974, 2015). "Specifically, activation of RhoA has been linked with induction of apoptosis in tumor stem cells and in prostate cancer." (PMID 24284827, 2013). "For example, it has been shown that GnRH-mediated attenuation in migration capacity of DU145 cells (prostate cancer-derived) is associated with an increase in the amount of stress fibers and with RhoA activation as well." (PMID 23176180, 2012). "Furthermore, the inhibition of RhoA activity due to loss of actin/myosin microfilaments in prostate cancer cell cultures was also observed after the administration of the exogenous CB1 agonist, anandamide." (PMID 34439262, 2021). "Moreover, a significant overlap exists between the genomic changes associated with different stages of prostate cancer progression with those induced by oncogenic RhoA mediated transformation, suggesting that this is an important pathway for prostate tumor progression in humans." (PMID 25623341, 2015). "Peptide toxins such as JZTX-I, which activate Nav1.7, can upregulate the expression of cytoskeleton-related proteins and activate the Rho GTPases-RhoA/Rac1 signaling pathway in prostate cancer cells." (PMID 41163355, 2025). "ARHGEF2 promotes cell migration and invasion in gastric and prostate cancer via RhoA/ROCK activation." (PMID 36159187, 2022). "On the other hand, some studies have suggested that mTOR complexes regulate EMT via RhoA and Rac1 signaling pathways in prostate cancer." (PMID 33920031, 2021). "OTUB1 activates RhoA to promote prostate cancer cell invasion and promote tumorigenesis in prostate cancer." (PMID 33498168, 2021). "On this basis, reducing cell motility through interference in the mediation of RhoA signaling via cannabinoids receptors represents another pharmacological application against prostate cancer." (PMID 34439262, 2021). "Genetic variants in RhoA and ROCK1 genes have been suggested as susceptibility factors for prostate cancer development." (PMID 32872192, 2020). "In mammary and prostate carcinoma CB1 activation led to a reduced motility via the phosphorylation of FAK or a reduced RhoA phosphorylation." (PMID 30753211, 2019). "Genetic variants of RhoA and ROCK1 genes have been suggested as susceptibility factors for prostate cancer development." (PMID 31557128, 2019). "It has been reported that RhoA is a mediator of androgen-regulated migration in prostate cancer cells." (PMID 30886905, 2019). "Taken together, the results in our present study provided new insight into genetic variants in RhoA/ROCK1 signaling pathway and their function in prostate cancer." (PMID 28184030, 2017). "Ras homolog family member A (RHOA) regulates clinically relevant androgen action in prostate cancer cells." (PMID 28425476, 2017). "Skp2 is a transcriptional target of STAT3, which, along with downstream genes (including RhoA), can stimulate prostate cancer metastasis and proliferation." (PMID 28157698, 2017). "Our study is the first to clarify the relations of genetic variants of RhoA and ROCK1 genes with development, progression and prognosis of prostate cancer." (PMID 28184030, 2017). "Istaroxime induced apoptosis, affected the key proliferative and apoptotic mediators c-Myc and caspase-3 and modified actin cystoskeleton dynamics and RhoA activity in prostate cancer cells." (PMID 27027435, 2016).
prostate carcinoma (continued). "Our RNAi screening identified OTUB1 as an important regulator of prostate cancer cell invasion through the modulation of RhoA activation." (PMID 25623341, 2015). "Recent studies have found that miR-34a represses RhoA, a regulator of cell migration and invasion, by suppressing c-Myc–Skp2–Miz1 transcriptional complex that activates RhoA in human prostate cancer cells." (PMID 26077733, 2015). "We found that OTUB1 plays a critical role not only in the AR-dependent but also AR-independent cell invasion of prostate cancer cells in vitro and in vivo through the modulation of RhoA activity." (PMID 25623341, 2015). "In summary, we demonstrate that OTUB1-mediated activation of RhoA promotes cell invasion of prostate cancer cells." (PMID 25623341, 2015). "Previous studies have shown that RhoA and NF-κB activity were essential for high PC-3 prostate cancer cell invasion." (PMID 26317041, 2015). "In this study we have demonstrated that OTUB1 protein levels are elevated in prostate cancer and contribute to the induction of cell invasion through a mechanism that involves the activation of RhoA." (PMID 25623341, 2015). "OTUB1 mediates prostate cancer cell invasion through RhoA activation and promotes tumorigenesis in vivo." (PMID 25623341, 2015). "EphA2 overexpression in prostate cancer cells has been shown to increase migration via activation of Src and RhoA or via Akt in a ligand-independent manner." (PMID 24795148, 2014). "We show that EphA receptors signal via the exchange factor Vav2 to activate RhoA and that both Vav2 and RhoA are required for prostate cancer cell–cell repulsion." (PMID 24795148, 2014). "We show with several methods that strong RhoA activation induced by the bacterial toxin CNFy leads to intrinsic apoptosis in the androgen-dependent prostate cancer cell line LNCaP." (PMID 24284827, 2013). "Activated EphA4 and EphA2 have been shown to trigger the activation of RhoA, which ultimately led to reinitiation of migration in a different direction in a prostate cancer cell line." (PMID 23738943, 2013). "Here, we show that activation of RhoA by the specific Rho activator CNFy is sufficient to induce apoptosis in the prostate cancer cell line LNCaP." (PMID 24284827, 2013). "In prostate carcinoma PC-3 cells, RhoA is a critical endogenous promoter of cell invasion and migration." (PMID 23056431, 2012). "Similarly, the presence of CB2-CXCR4 heteromers results in a reduction in Ga13/RhoA signaling, leading to inhibition of cell migration and invasion in prostate cancer." (PMID 35328467, 2022). "In prostate cancer, suppressing RhoA/ROCK1 signaling inhibits cellular proliferation and EMT." (PMID 34486491, 2021). "To gain initial insights into the possible modulation of the CTD code by Rho signaling in human cells, we used the relatively specific inhibitors for RhoA, Rac and Cdc42 in two human cancer cell lines: the prostate cancer DU145 cell line, and the cervical carcinoma HeLa cell line." (PMID 32143485, 2020). "OTUB1 mediates prostate cancer tumorigenesis and invasion through RhoA activation." (PMID 31737118, 2019). "RhoA activity was measured in relation with OTUB1 effects on prostate cancer cell invasion." (PMID 25623341, 2015).
prostate carcinoma (continued). "While RhoA activation induces tail release and more rounded cell morphology, the inhibition of its downstream effector ROCK by Y-27632 is associated with an elongated morphology in PC3 human prostatic cancer cells, NIH 3T3 fibroblasts, and podocytes." (PMID 23209630, 2012). "Interestingly, we found that RhoA inhibition was predominantly effective in LNCaP prostate cancer cells, which aligns with the previously demonstrated importance of RhoA in this type of malignancy and suggests combined co-inhibition of RhoA and SRCs as a potential treatment for prostate cancer." (PMID 33767353, 2021). "Moreover, the inhibitory effect of rapamycin on expression of RhoA is also observed in other tumor cell lines, including those derived from cervical cancer (HeLa), prostate cancer (PC-3), Ewing sarcoma (Rh1), and glioblastoma (U-373), suggesting that this is not cell-type dependent." (PMID 24605059, 2014). "The mechanism of RhoA activation downstream of EphA receptors in prostate cancer cells is unknown but a number of GEFs such as Ephexin or Vav have been shown to be required for EphA-induced growth cone collapse, an event that closely resembles cell retraction during CIL." (PMID 24795148, 2014). "Analysis indicated that the 9 hub genes (AKT1, HSP90AA1, SRC, GSK3β, VEGFR2, RHOA, ENO1, PKM, and IL-2) play roles in MF treatment by participating in signaling pathways related to prostate cancer, lipid and atherosclerosis, and insulin resistance." (PMID 40051434, 2025). "Treatment of prostate carcinoma cells with the selective CB1 agonist WIN55,212–2 led to a decrease in migration with a significant diminishing of RhoA activity, while treatment with CB1 selective antagonist AM251 showed a significant increase in RhoA activity." (PMID 34313032, 2022). "We have not proved the importance of PA2G4 and Ki67 for CaP detection as they weakly correlated with some prostate cancer-related markers (e.g., AMACR), but also with leukocyte-specific CD45 and house-keeping genes (TBP and RHOA)." (PMID 32630458, 2020). "Key among the findings which may account for the aberrant activation of the AR in prostate cancer was the discovery that, in addition to classical ligand-binding mechanisms, transcriptional activity of the AR is controlled through its direct binding to the RhoA effectors PRK1 and PRK2." (PMID 26296974, 2015). "Here we find that Vav2 is required for RhoA activation downstream of EphA receptors and EphA receptor–RhoA-mediated CIL in prostate cancer cells." (PMID 24795148, 2014). "Inhibition of RhoA or its major downstream effector, ROCK1, diminishes motility of prostate carcinoma cells." (PMID 23056431, 2012). "In human prostate carcinoma cells, Epac inhibits proliferative and migratory responses likely because of inhibition of MAP kinase and RhoA signalling pathways." (PMID 19920825, 2009). "In summary, this study shows for the first time anti-proliferative and anti-migratory effects of Epac activation in human prostate cancer cells, presumably mechanistically explained by an inhibition of the MAP kinases and RhoA." (PMID 19920825, 2009). "While the prognostic value of HDGF has not yet been evaluated before, previous studies have shown that downregulation of HDGF inhibited migration and invasion of prostate cancer cells, and HDGF activated the MAPK/ERK pathway via KRAS and RhoA mediation in cell line models of prostate cancer." (PMID 39402324, 2024). "In human prostate carcinoma cells, TGF-β treatment induced a rapid formation of lamellipodia through the SMAD-independent signaling pathway, which requires the activation of the Rho-family GTPases including CDC42 and RHOA." (PMID 35151689, 2022). "By extending the drug-gene vulnerabilities evaluation beyond the MCF-7 cell line, we discovered that highly potent cancer-killing combinations of SI-12 can also be achieved in triple-negative breast cancer (TNBC), pancreatic, and prostate cancer cells with DNMT and RhoA inhibitors." (PMID 33767353, 2021).
prostate carcinoma (continued). "The regulatory pathways SOX5-NEDD4L/PBX3, miR429-GNAQ/ANLN—RHOA, and miR429-ANLN—KIF11 may participate in the progression of the androgen-independent phenotype in prostate cancer." (PMID 29324665, 2018). "A study published in PNAS surveyed endothelial cells (ECs) of transgenic mice bearing prostate adenocarcinoma and indicated that high level of baseline activity of RhoA and ROCK1 might give rise to aberrant behaviors of prostate cancer ECs." (PMID 28184030, 2017). "The contribution of genetic variants in RhoA and ROCK1 genes towards prostate cancer risk has not been reported before." (PMID 28184030, 2017). "Furthermore, the mRNAs of Skp2, RhoA, and SNAI1 were identified through q-PCR to be decreased in the DT-treated prostate cancer cells." (PMID 28157698, 2017). "However, the functional requirement for RhoA in prostate cancer contact repulsion has not been shown." (PMID 24795148, 2014). "In androgen-independent prostate cancer cells, AZA1 inhibited both Rac1 and Cdc42 but not RhoA GTPase activity in a dose-dependent manner and blocked cellular migration and proliferation." (PMID 24040362, 2013). "Of interest, the tumor suppressor maspin has been reported to mediate tumor cell migration through inhibiting Rac1 and Cdc42, but not RhoA GTPase, suggesting that targeting the Rac1/Cdc42 pathways by AZA1 could counteract the activity of maspin in prostate cancer cells." (PMID 24040362, 2013).
hepatocellular carcinoma (64 papers, 2008 to 2025). A malignant tumor that arises from hepatocytes. "Further, overexpression of RhoA is associated with capsule invasion, portal vein invasion, dissemination, venous invasion and microscopic satellite legions in hepatocellular carcinomas." (PMID 31976530, 2020). "The aim of this study was to investigate the expression level of Ras homolog gene family, member A (RhoA) in patients with hepatocellular carcinoma (HCC) and to investigate the prognostic and diagnostic value of RhoA." (PMID 31339860, 2019). "We investigated the molecular mechanism underlying CD147 induced RhoA deactivation in hepatocellular carcinoma (HCC) cells." (PMID 27601938, 2016). "Our previous study revealed that overexpression of RhoA was associated with poor prognosis in hepatocellular carcinoma." (PMID 18651974, 2008). "Specifically, Vav1 synergizes with KRAS mutations to promote pancreatic cancer, while GEF–H1 facilitates hepatocellular carcinoma (HCC) metastasis by modulating RhoA‐dependent cytoskeletal changes." (PMID 41020039, 2025). "Recently, it has been shown that RhoA interacts with TRPM7 through its kinase activity in hepatocellular carcinoma cells." (PMID 40274768, 2025). "Although it has been proven to promote hepatocellular carcinoma, RhoA is considered to be a tumor suppressor in some cancers." (PMID 39858398, 2024). "On the contrary, SPON2 prevented F-actin assembly, thereby inhibiting hepatocellular carcinoma cell migration by α5β1 integrin inactivated RhoA." (PMID 34583750, 2021). "A recent study described that the RhoA/ROCK pathway was involved in the VM process in a hepatocellular carcinoma (HCC) cell line." (PMID 34638872, 2021). "SPON2 can enhance M1-like macrophage recruitment to repress hepatocellular carcinoma by regulating RhoA pathways." (PMID 33552977, 2020). "The role of RND1 in EMT has been extended to hepatocellular carcinoma cells, in which the depletion of RND1 also causes EMT, this time via the activation of RHOA." (PMID 31344837, 2019). "One small molecule inhibitor, Rhosin, inhibits RHOA signaling by directly targeting the RHOA protein, in breast and hepatocellular cancer cells, as well as GC cells." (PMID 31156701, 2019). "miR-494-3p was further shown to target ROCK1, while miR-122 has been demonstrated to modulate RhoA and influence motility of hepatocellular carcinoma cells." (PMID 29343687, 2018). "A prognostic value of RhoA has also been observed in hepatocellular carcinoma, where a strong expression predicts a shorter survival rate." (PMID 23420497, 2013). "Although the functional connection between FAK and RhoA has been reported in many human cancers, how Grp78 inhibited Rock activity in hepatocellular carcinoma should be elucidated." (PMID 20082722, 2010). "Hypoxia also promotes remodeling of the actin cytoskeleton and cancer cell motility through the activation of the RhoA/Rho-associated protein kinase (ROCK) signaling pathway by HIF-1α, which leads to increased invasion and migration of hepatocellular carcinoma (HCC) cells in vitro and in vivo." (PMID 37490147, 2023). "Previous studies have shown that StarD13 inhibits RhoA in hepatocellular carcinoma cells." (PMID 32900380, 2020). "CTHRC1 promotes hepatocellular carcinoma cell invasion by activating the RhoA/Rho-associated kinase (ROCK) pathway and facilitates adhesion of hepatocellular carcinoma cells to ECM through induction of integrin β1 expression and activation of focal adhesion kinase (FAK)." (PMID 32848510, 2020). "BOP1 could promote the epithelial‐to‐mesenchymal transition by stimulating actin stress fiber assembly and RhoA activation in hepatocellular carcinoma." (PMID 32167616, 2020). "In line with this hypothesis, transfection of the dominant active RhoA into rat hepatoma cells was shown to induce the peripheral distribution of cathepsin D and of LIMPI-positive lysosomes, and the formation of stress fibers." (PMID 32111095, 2020).